CCR2 (C-C motif chemokine receptor 2)
Diseases named in the same sentence as CCR2 in open-access papers (continued):
Sharing a sentence is not in itself a finding about the gene and the disease.
parasitemia (continued). "Group 1 patients, characterized by an elevated percentage of CD14hi CCR2+CX3CR1+ MO, had a low mean parasitemia." (PMID 19851453, 2009). "Similar to the CCR2-/- mouse, the CCL2/CCR2 double knock-out mouse is unable to clear parasitic infections despite higher than normal interferon-γ production than the CCR2 deficient mouse." (PMID 17888174, 2007). "CCR2−/− mice treated at day 5 and 6 post-infection still die of ECM and have the same parasitemia as CCR2−/− non-treated mice." (PMID 21494565, 2011). "Group 2 patients, characterized by a percentage of CD14hi CCR2+CX3CR1+ MO similar to that of healthy malaria exposed individuals, had a pro-inflammatory phenotype, a trend for higher levels of plasma cytokines, and a 10 fold higher mean peripheral parasitemia." (PMID 19851453, 2009). "Neither total peak parasitemia nor duration of parasitemia were affected by the lack of CCR2." (PMID 39452729, 2024). "Mice lacking CCR2, a chemokine receptor involved in the recruitment of inflammatory monocytes, and mice lacking NADPH oxidase, which generates superoxide radicals, demonstrated reduced parasite killing but had little effect on the course of parasitemia." (PMID 39452729, 2024). "Moreover, after anti-CXCR3 treatment, all mice had an increased parasitemia and burden of tissue parasitism, and died due to infection, showing that CXCR3, but not CCR2, had a pivotal role in T. cruzi resistance." (PMID 31356587, 2019).
pancreatic ductal adenocarcinoma (17 papers, 2020 to 2025). An infiltrating adenocarcinoma that arises from the epithelial cells of the pancreas. "A study conducted in a mouse model of pancreatic ductal adenocarcinoma found particularly high levels of neutrophils expressing C-C chemokine receptor type 2 (CCR2) in the brain of mice early in the disease development." (PMID 40362192, 2025). "In a clinical trial for pancreatic ductal adenocarcinoma, combination treatment with the CCR2 antagonist BMS-813160 and anti-PD-1 was determined to be safe with only one grade 3 or higher adverse event in a single patient." (PMID 39307417, 2024). "CCR2 in combination with FOLFIRINOX for advanced pancreatic ductal adenocarcinoma is in clinical phase II (NCT01413022)." (PMID 35770088, 2022). "CCR2 blocking has been shown to suppress tumor growth in murine liver cancer and pancreatic ductal adenocarcinoma models." (PMID 34885241, 2021). "Furthermore, small molecule inhibitors that target CXCR2 on neutrophils and CCR2 on macrophages have demonstrated the ability to enhance the chemotherapeutic effects in models of pancreatic ductal adenocarcinoma." (PMID 37892995, 2023). "Moreover, PPARδ was found to dramatically accelerate pancreatic ductal adenocarcinoma development by activating the PPARδ-CCL2/CCR2 axis or the GOT2-PPARδ axis to drive immunosuppression through suppressing T cell-mediated anti-tumor immunity." (PMID 37572185, 2023). "Additionally, CCR2 combined with Abraxane and Gemcitabine for metastatic pancreatic ductal adenocarcinoma is in phase Ib/II (NCT02732938) clinical trial." (PMID 35770088, 2022). "In clinical applications, the combination of the oral CCR2 small molecule antagonist PF-04136309 with conventional chemotherapy resulted in partial tumor responses (49%) and local tumor control in 97% of patients with advanced pancreatic ductal adenocarcinoma (PDAC)." (PMID 37892995, 2023). "Furthermore, a recent clinical study of PF-04136309, a CCR2 inhibitor, in combination with nab-paclitaxel and gemcitabine has found severe adverse effects by this regimen including pulmonary toxicity in patients with pancreatic ductal adenocarcinoma." (PMID 34885241, 2021). "CCR2 antagonists (such as BMS-813160, PF-04136309, and CCX872) are in clinical trials for pancreatic ductal adenocarcinoma (ClinicalTrials.gov [Internet]." (PMID 39185154, 2024). "A phase 1b clinical trial showed that following administration of PF-4136309 in patients with pancreatic ductal adenocarcinoma (PDAC), levels of CD14 + CCR2+ inflammatory monocytes reduced in the peripheral blood." (PMID 39076996, 2024).
retinal degeneration (17 papers, 2011 to 2025). Degeneration of the retina. "Previous studies have shown that the mice with Cx3cr1 deficiency developed retinal degeneration by 1–2 years of age, and the pathology is known to be related to increased subretinal infiltration of CCR2+ phagocytes and the impairment in their removal." (PMID 33602265, 2021). "Chronic CCR2+ inflammatory monocyte recruitment has recently been shown to mediate photoreceptor degeneration in other models of retinal degeneration and AMD." (PMID 24142887, 2013). "Nevertheless, the models allowed us to investigate the casual roles of monocyte malfunction (as a result of CCL2 or CCR2 depletion) in age-related retinal degeneration." (PMID 21850237, 2011). "CCR2 has been reported to be expressed in macrophages in an inherited retinal degeneration model." (PMID 35955937, 2022). "Hence, in this preclinical model of retinal degeneration, C5 activation critically contributes to photoreceptor and RPE cell loss through C5a-mediated recruitment of pathogenic peripheral blood Ly6ChiCD88+CCR2+ monocytes to the outer layers of the retina." (PMID 29743491, 2018). "Conversely, it has been previously suggested that aging Ccl2−/− Ccr2−/− mice develop AMD-like retinal degeneration, indicating that a degree of Ccl2 signaling is also required for homeostasis, although the AMD-like phenotype in the knockout has been questioned." (PMID 22992301, 2012). "Thus, Ccr2 expression in microglia is a feature of their activation during retinal degeneration." (PMID 26458944, 2015). "Compared to normal mice, retinal degeneration in CX3CR1−/− mice was paralleled by increased CCL2 induction and retinal CCR2+ monocytes infiltration." (PMID 28320442, 2017). "CCR2 deletion blocked retinal degeneration, suggesting that CX3CR1 usually represses CCL2 over-induction and recruitment of neurotoxic levels of CCR2+ monocytes." (PMID 28320442, 2017). "Ccr2 is a therapeutic target for retinal degenerative disorders including AMD and RP because deletion of Ccl2, a cognate ligand for Ccr2, can rescue PCD in Mertk−/− mice and deletion of Ccr2 ameliorated retinal degeneration in another model." (PMID 26458944, 2015). "The CCL2/CCR2 axis is crucial in subretinal macrophage and microglia accumulation in retinal degeneration models and human AMD, and these findings implicate that CCL2/CCR2 inhibition may be a novel tool to limit inflammation and neurodegeneration in the retina." (PMID 26527153, 2015).
steatosis (17 papers, 2009 to 2025). Increased lipid within the cytoplasm of cells. "In contrast, MCP-1- or CCR2-deficient mice have attenuated HF diet-induced steatosis and macrophage infiltration." (PMID 21274430, 2010). "Previous studies have shown that increased hepatic CCL2 recruits CCR2-positive monocytes, exacerbating inflammation, fibrosis, and steatosis in MASLD patients." (PMID 40507104, 2025). "We also found increased levels of triglycerides, alanine aminotransferase (ALT), Ccr2, and Col1a1 mRNAs, which indicate steatosis, hepatocellular damage, liver inflammation, and collagen deposition." (PMID 38817615, 2024). "CCR2-/- or CCR2 inhibitor treatment in mice alleviates steatosis, inflammatory cell infiltration, and fibrosis." (PMID 34956171, 2021). "In the HIV-Tg rats, binge alcohol increases LPS/endotoxin-mediated hepatic leptin and TLR4 level, which further activated Kupffer cells with up-regulated levels of MCP-1 and CCR2, at least partially, contributing to greater hepatic inflammation and steatosis." (PMID 26484872, 2015). "Collectively, our studies show that CD44 and CCR2 contribute to hepatitis in a model of NAFLD despite histological evidence of steatosis and elevated serological markers of hepatocellular damage." (PMID 23762326, 2013). "This suggests that MCP-1 and its receptor CCR2 contribute to the metabolic syndrome including obesity-related steatosis." (PMID 21274430, 2010). "Conversely, knock-out of Ccl2 or its receptor Ccr2, improves insulin sensitivity and prevents steatosis." (PMID 19513120, 2009). "Moreover, in an experimental model, the pharmacological targeting of CCR2 antagonist prevented steatosis and reduced macrophage infiltration." (PMID 33042108, 2020). "Taken together, these data indicate that Ccr2−/− are completely protected and Cd44−/− mice are partially protected from hepatic inflammation despite similar histological evidence of steatosis and serological evidence of hepatocellular damage when compared to B6 mice." (PMID 23762326, 2013). "When upregulated, CCR2 can induce macrophage accumulation, inflammation, fibrosis and steatosis and the CCL2/CCR2 axis can influence cell growth, angiogenesis, invasion and metastasis." (PMID 34251980, 2021). "The authors used cenicriviroc (CVC), a dual inhibitor of CCR2/5, to inhibit CCR2/5 signaling in a mouse model of ALD, which reduced liver damage and steatosis." (PMID 33076386, 2020). "Within the context of MASLD, various cell types (i.e., KCs, infiltrating macrophages, hepatocytes, and activated HSCs) produce MCP-1, which attracts C-C chemokine receptor type 2 (CCR2)+ monocytes within the liver, possibly promoting hepatic steatosis and fibrosis." (PMID 40794228, 2025). "Recently, pharmacological inhibition of MCP-1 or the lack of CCR2 expression (MCP-1 receptor) in a murine model of NASH was shown to decrease liver inflammation and steatosis without affecting hepatic fibrogenesis." (PMID 24039859, 2013).
breast tumor (14 papers, 2017 to 2023). "In future studies, it would be of interest to examine how CCR2 coordinates breast tumor growth and invasion with other oncogenic factors." (PMID 31208996, 2019). "CCL2 recruits CCR2-expressing inflammatory monocytes to facilitate breast tumor metastasis." (PMID 30151375, 2018). "In human breast tumor tissues, CD154 expression inversely correlated with CCR2 expression and correlated with relapse-free survival." (PMID 37208442, 2023). "In a murine breast tumor model, targeting the CCL2-CCR2 axis by complexes of CCR2 siRNAs and TAT cell penetrating peptides enhanced the efficacy of immunotherapy and promoted the reprogramming of TAMs." (PMID 34683963, 2021). "Expression of CCR2, the main CCL2 receptor, in both TNC+ and TNC− NT193 breast tumor cells was below 0.5% of HPRT for all timepoints in both cell types, suggesting that whilst tumor cells are a major source of CCL2, they are not responding in an autocrine manner to this chemokine." (PMID 37176074, 2023). "Furthermore, the expression of CCR-2 is up-regulated in breast tumor cells, and knockdown of CCR-2 expression inhibits breast tumor development." (PMID 28420351, 2017).
injury (14 papers, 2016 to 2025). Damage inflicted on the body as the direct or indirect result of an external force, with or without disruption of structural continuity. "Among the upregulated genes, CCR2 encodes the main chemokine receptor required for monocyte migration from the bone marrow to inflammatory sites and plays a key role in the damaging effects of neuroinflammation following traumatic brain injury." (PMID 36528616, 2022). "One study investigated the role of CCR2+ monocytes in lung inflammation and found that these cells were responsible for recruiting neutrophils to the lungs in a mouse model of acute lung injury." (PMID 38596679, 2024). "We also used genetic (CCR2RFP/ RFP, CCR2 knockout) and pharmacological methods (RS102895, a CCR2 antagonist) to test the roles of monocytic influx in LPS/HI brain injury." (PMID 34976198, 2022). "It was recently described that CCL2 and its receptor CCR2 regulate macrophage trafficking by induction of leukocyte adhesion to the microvascular endothelium after brain injury." (PMID 31660990, 2019). "In a model of traumatic brain injury, blockade of CCR2 signaling prevented recruitment of monocytes to the brain during a short window period following the injury." (PMID 26862765, 2016). "It has been reported that (R)-4-Acetyl-1-(4-chloro-2-fluorophenyl)-5-cyclohexyl-3-hydroxy-1,5-dihydro-2H-pyrrol-2-one (CCR2 RA [R]), a CCR2 antagonist, at 14 and 28 days after nerve injury significantly reduced bilateral nociceptive behavior (pain sensitivity)." (PMID 39076996, 2024). "In other studies on the effect of the CCR2 KO on the development of MA-ARDS or malaria-associated acute lung injury, similarly no or only modest differences between CCR2 WT and KO mice are detected." (PMID 33664739, 2020). "To clarify the functions of CCR2-positive MSC-exos in vivo, we therefore established an I/R-induced renal injury mouse model and compared the effects of CCR2-positive and CCR2 knockdown MSC-derived exosomes with those of the NIH3T3 cells or NC RNA-transfected MSCs as controls." (PMID 27843457, 2016). "The underlying mechanism may be that PER1 interacts with PPAR-γ in the promoter region of the CC chemokine receptor 2 (Ccr2) gene, thereby enhancing PPAR-γ-mediated transcriptional inhibition of Ccr2 and attenuating excessive innate immune responses in endotoxin-induced liver injury." (PMID 41451215, 2025). "In this phase following nerve injury, the CCL2/CCR2 axis is essential in maintaining pain hypersensitivity." (PMID 39076996, 2024). "Additionally, repeated administration of this dual CCR2/CCR5 antagonist enhanced the analgesic effects of morphine and buprenorphine in neuropathic rats, which can be associated with the ability of cenicriviroc to prevent nerve injury-induced downregulation of all opioid receptors at the DRG level." (PMID 33408720, 2020). "We herein elucidated the impact of chemokine receptor inhibition by the dual CCR2 and CCR5 inhibitor cenicriviroc (CVC) on the composition of myeloid and lymphoid immune cell populations in acute liver injury." (PMID 28910354, 2017). "The CD45high/CD11b+ cell population plays an important role in phagocytosis and in the monocyte/macrophage composition of various subpopulations with or without CCR2 expression, and we observed at least two clusters of CD45high/CD11b+ populations involved in post-hemorrhagic brain injury." (PMID 36545808, 2023).
myocarditis (14 papers, 2010 to 2025). Myocarditis is a condition that is characterized by inflammation of the heart muscle (myocardium). "Administration of cDNA encoding chemokine receptors (CCR2 and CxCR3) prevented dilated cardiomyopathy and death in a model of myocarditis, presumably acting as a decoy receptor and targeted deletion of CCR2 reduced ventricular remodeling after experimental MI." (PMID 23936109, 2013). "As for myocarditis, the expansion of CXCL9/10+CCR2+ macrophages and CXCR3hi CD8+ T lymphocytes is linked to the pathogenesis of ICI‐associated myocarditis, highlighting the therapeutic potential of CXCR3 pathway modulation." (PMID 40787068, 2025). "In a myocarditis mouse model, silencing of CCR2 prevented cardiac monocyte accumulation and chronic decline of LV function." (PMID 39994453, 2025). "Further analysis of Adrb2 expression on CCR2+MHCIIhigh MoMFs in the myocarditis‐afflicted and normal control groups revealed a decrease in Adrb2 expression in the myocarditis group." (PMID 39601476, 2024). "These monocytes also expressed CCR2, which enables migration to sites of tissue injury as well as differentiation into inflammatory cardiac macrophages, including in myocarditis." (PMID 37146127, 2023). "Delayed silencing of CCR2 improved late-stage disease outcomes for myocarditis in mice at 60 dpi by reducing inflammation and fibrosis." (PMID 37175422, 2023). "Heart tissue biopsies from patients with myocarditis revealed an increase in the number of monocytes that express CCR2." (PMID 37175422, 2023). "Chemokines, including the ligands of CCR5 and CCR2, are important to the mechanism that leads to myocarditis." (PMID 20169058, 2010). "The silencing of CCR2 in CVB3-infected mice significantly was shown to reduce the accumulation of lymphocyte antigen 6 complex (Ly6C) high monocytes in cardiac tissue during acute myocarditis." (PMID 37175422, 2023). "CCR2 silencing in mice with acute myocarditis reduced the migration of granulocyte-macrophage progenitor cells from the bone marrow into the blood, suggesting that this strategy may indicate a pathway for successful treatment of myocarditis." (PMID 34578651, 2021). "Both MCP-1 and CCR2 play a pivotal in the CVB3-induced myocarditis pathogenesis." (PMID 28800592, 2017). "In addition, we further analyzed the changes of macrophages and their subsets CCR2+ macrophage derived from and slowly replenished by circulation blood monocytes in myocarditis, and their infiltration in the heart was regarded as pathological and proinflammatory." (PMID 37069636, 2023). "In one study, siRNA against chemokine (C–C motif) receptor 2 (CCR2), a chemokine receptor critical for leukocyte migration, was encapsulated in nanoparticles to treat inflammatory cell infiltration of the heart and subsequent deterioration of cardiac function in myocarditis." (PMID 34578651, 2021). "Cardiac tissue biopsy samples from patients with myocarditis were enriched for CCR2+ cells and had elevated CCL2 and CCR2 mRNA expression compared to control specimens obtained from individuals dying from trauma with no history of cardiac disease." (PMID 36110847, 2022). "This follows from the findings that CX3CR1-/- CVB3 mice exhibited an exacerbated CVB3-induced myocarditis as shown by a higher LV MCP-1 and CCR2 expression, more cardiac infiltrates, and higher cytokine levels versus CVB3-infected WT mice." (PMID 28800592, 2017). "Similarly, the expansion of CCR2+ CXCL9/10+ macrophages, along with CXCR3hi CD8+ T cells, was seen in a preclinical model of myocarditis in MRL/Pdcd1−/− mice." (PMID 39023770, 2025). "Furthermore, CX3CR1 seems to control the CCR2/MCP-1-dependent pathway, since CX3CR1 ablation resulted in an exacerbation of CVB3-induced myocarditis." (PMID 28800592, 2017). "Furthermore, we showed an increased expression of the chemokine MCP-1 and its receptor CCR2 in cardiac and splenic tissue of CVB3-induced myocarditis versus control mice." (PMID 28800592, 2017).
non-small cell lung carcinoma (14 papers, 2017 to 2025). A group of at least three distinct histological types of lung cancer, including non-small cell squamous cell carcinoma, adenocarcinoma, and large cell carcinoma. "CAR-T cells against CCR2b antigen expressed in B cells have potent antitumor activity against non-small cell lung cancer, with notable promise in targeting brain metastases via engineering of the CCL2/CCR2 axis." (PMID 39065701, 2024). "Their findings suggest that the CCL2/CCR2 axis enhances the migration of CAR-T cells into brain metastases of non-small cell lung cancer." (PMID 36359834, 2022). "Targeting CCR2 with its antagonist also suppresses viability, motility, and invasion by downregulating MMP-9 expression in non-small cell lung cancer cells." (PMID 33297571, 2020).